IGF1R (insulin like growth factor 1 receptor)
Diseases named in the same sentence as IGF1R in open-access papers (continued):
Sharing a sentence is not in itself a finding about the gene and the disease.
hemangioma (5 papers, 2021 to 2025). A benign vascular lesion characterized by the formation of capillary-sized or cavernous vascular channels. "In our genetic analysis of the hemangioma-related genes, infants with the allele G of the insulin-like growth factor-1 receptor (IGF-1R3174 G > A) were 50% less likely to develop moderate or severe IVH (OR: 0.5, p = 0.037)." (PMID 36656337, 2023). "In hemangioma stem cells, miR-139-5p can affect cell proliferation, migration, and adipogenesis through targeting insulin-like growth factor 1 receptor (IGF-1R)." (PMID 34725544, 2021). "Moreover, miR-139-5p suppressed the migration of hemangioma stem cells (HemSCs) by targeting the insulin-like growth factor 1 receptor (IGF-1R), which plays a role in the regulation of the IGF-1/IGF-1R signaling pathway." (PMID 40710326, 2025). "Our research group previously investigated miR-139-5p and revealed its influence on hemangioma stem cells’ (HemSC) proliferation, migration, and adipogenesis by modulating the IGF-1/IGF-1R pathway." (PMID 38393667, 2024).
hyperthyroidism (5 papers, 2022 to 2025). Overactivity of the thyroid gland resulting in overproduction of thyroid hormone and increased metabolic rate. "TED is mediated by antibodies targeting the thyroid-stimulating hormone receptor (TSHR) and the insulin-like growth factor-1 receptor (IGF1R), which leads to hyperthyroidism." (PMID 41227354, 2025). "An anti-IGF-1R antibody, teprotumumab, has recently been shown to be effective in attenuating various TED manifestations in a phase II clinical trial, further supporting the potential therapeutic significance of targeting HMGCR in hyperthyroidism." (PMID 38425755, 2024).
invasive carcinoma (5 papers, 2013 to 2023). A carcinoma that is not confined to the epithelium, and has spread to the surrounding stroma. "For example, our results show that the overexpression of miR-15b had a profound effect of the IGF1R levels in M6 cells (invasive carcinoma) compared to M6C (metastatic) cells." (PMID 37686596, 2023). "TIMER2.0 was used to identify the correlation between EGFR and other gene expressions in breast-invasive carcinoma subtypes with purity adjustments such as FGF2, FGFBP1, TGFA, TGFBR3, and IGF1R in all BRCA patients." (PMID 36430763, 2022). "Pooled expression prevalence rates of carcinoma in situ were at least comparable to (GLUT1 and IGF1R) or higher than (CAIX and CXCR4) invasive carcinoma, albeit based on few studies." (PMID 24206539, 2013).
keloid (5 papers, 2013 to 2025). An irregularly shaped, elevated mark on the skin caused by deposits of excessive amounts of collagen during wound healing. "The insulin signalling pathway was activated in keloid lesions with highly upregulated insulin-like growth factor 1 receptor (IGF1R)." (PMID 35709140, 2022). "Similarly, CD26 drives keloid fibroblast proliferation and invasion through IGF-1/IGF-1R-mediated PI3K/Akt/mTOR activation, promoting mTOR downstream effectors (P70S6K, 4E-BP1); inhibition of CD26 or IGF-1R abrogates these effects, underscoring their central role in keloid progression." (PMID 41424791, 2025).
malignant glioma (5 papers, 2014 to 2023). A grade III or grade IV glioma arising from the central nervous system. "IGF/IGF-1R signaling has been implicated in malignant gliomas, suggesting it a potential therapeutic target." (PMID 26035416, 2015). "Previous studies have shown that the insulin-like growth factor-1 receptor (IGF-1R) gene is amplified at high frequency in pediatric high-grade gliomas and is the second most frequently amplified gene in diffuse intrinsic pontine glioma (DIPG)." (PMID 37259440, 2023). "High-grade glioma (HGG) is highly resistant to therapy, prompting us to investigate the contribution of insulin-like growth factor receptor (IGF-1R), linked with radioresistance in other cancers." (PMID 31857716, 2020).
metastasis (5 papers, 2010 to 2023). The spread or migration of cancer cells from one part of the body (where they first appeared) to another. "This study didn’t show PTHrP and IGF-1R overexpression in NSCLC tissue related NSCLC bone metastasis." (PMID 22537906, 2012). "By multivariate analysis for disease-free interval, IGF1R overexpression was no longer significantly associated with an earlier recurrence, new primary tumor and/or lymph node and distant metastasis (p = 0.13)." (PMID 26449867, 2015).
multiple sclerosis (5 papers, 2013 to 2024). A progressive autoimmune disorder affecting the central nervous system resulting in demyelination. "A similar effect with a reduction of inflammation was achieved by the conditional deletion of IGF1R in CD4+ cells in multiple sclerosis." (PMID 36105797, 2022). "However, the IGF1R pathway has been demonstrated to favor the T-helper-17 cell differentiation over that of the T-regs in multiple sclerosis." (PMID 38420122, 2024).
rectal cancer (5 papers, 2014 to 2023). A primary or metastatic malignant neoplasm that affects the rectum. "In one study, PROTAB effectively degraded the insulin-like growth factor 1 receptor (IGF1R) in rectal cancer patients while causing minimal degradation in normal organs." (PMID 37669923, 2023). "Other clinical correlations have been shown for rectal cancer, in which a worse response to radiation therapy was observed in patients with IGF-1R overexpression." (PMID 36835075, 2023).
sarcopenia (5 papers, 2011 to 2024). Progressive decline in muscle mass due to aging which results in decreased functional capacity of muscles. "Compromised IGF-1R signaling has also been implicated in muscle hypertrophy, atrophy and age-associated sarcopenia." (PMID 22195016, 2011). "As a result, we successfully identified a causal effect between IGF family members and sarcopenia, with higher levels of IGF-1, IGF-1R, IGFBP-3, and IGFBP-7 being associated with a reduced risk of sarcopenia." (PMID 39507055, 2024). "Elevated levels of IGF-1, IGF-1R, IGFBP-3, and IGFBP-7 within the IGF family are associated with a decreased risk of sarcopenia, indicating a causal associated with sarcopenia." (PMID 39507055, 2024). "The analysis of molecular pathways of IBD-related sarcopenia assessed by using immunohistochemistry showed a down-expression of IGF1-R and Phospho-mTOR, markers of muscle growth, and an over-expression of Murf-1 and Myostatin, considered markers of sarcopenia." (PMID 34326845, 2021). "Pinoresinol and vanillic acid, extracted from Catalpa bignonioides Walt, have been found to stimulate muscle cell proliferation through the insulin-like growth factor-1 receptor (IGF-1R)/AKT/mTOR pathway, potentially alleviating sarcopenia." (PMID 39062777, 2024). "In addition to IGF-1, within the IGF family, we found that IGF-1R increased whole body fat-free mass, and IGFBP-3 and IGFBP-7 increased appendicular lean mass, and improved muscle mass and muscle bulk, demonstrating that high IGF-1R, IGFBP-3, and IGFBP-7 levels may reduce the risk of sarcopenia." (PMID 39507055, 2024).
skin tumor (5 papers, 2015 to 2024). "This substantial decrease in susceptibility to skin tumor development is associated with reduced signaling through IGF-1R and the PI3K/AKT pathway." (PMID 39638246, 2024). "The greater ability of 3-epiCA and MA to inhibit skin tumor promotion was associated with greater reduction of Cox-2 and Twist1 proteins and inhibition of activation (i.e., phosphorylation) of IGF-1R, STAT3 and Src." (PMID 26513295, 2015). "However, the greater ability of 3-epiCA and MA to inhibit skin tumor promotion was associated with greater reduction of Cox-2 and Twist1 proteins and inhibition of activation (i.e., phosphorylation) of IGF-1R, STAT3 and Src." (PMID 26513295, 2015). "In skin cancer, LIMS1–neural precursor cells expressed a developmentally downregulated protein 4-insulin-like growth factor-1 receptor signaling axis, which is critical for promoting skin cancer cell proliferation and survival." (PMID 36901953, 2023). "Overexpression of IGF-1 in the keratin 5 (K5) positive epidermal basal cells activates IGF-1R signaling, which promotes downstream mitogenic and cell survival signaling, resulting in spontaneous skin tumor formation." (PMID 35401828, 2022). "As expected, the IGF-1R level was markedly reduced in the skin tumors of P1-K5 mice compared to the skin tumors of control mice." (PMID 35401828, 2022). "Collectively, these results suggest that depletion of PINCH-1 effectively inhibits IGF-1R expression, cell proliferation and skin tumor growth in vivo." (PMID 35401828, 2022). "The development and progression of skin cancers involve multiple signaling pathways including that of insulin like growth factor 1 receptor (IGF-1R)." (PMID 35401828, 2022). "Identification of signaling pathways that regulate IGF-1R is crucial for understanding the pathogenesis and therapeutic treatment of skin cancer." (PMID 35401828, 2022). "PINCH-1 as well as its downstream effector IGF-1R are expressed in not only skin tumors but also normal epidermis, albeit their expression levels in the latter are considerably lower than those in the tumors." (PMID 35401828, 2022). "Thus, elucidation of the mechanisms that control IGF-1R expression is crucial for understanding the pathogenesis of skin tumors and may provide new strategies for prevention and treatment of these deadly diseases." (PMID 35401828, 2022). "Furthermore, conditional PINCH-1 knockout mouse and carcinogen (7, 12-dimethylbenz[a]anthracene (DMBA)/12-O-tetradecanoylphorbol-13-acetate (TPA))-induced skin cancer model were employed to determine the function of PINCH-1 in regulation of IGF-1R expression and skin carcinogenesis in vivo." (PMID 35401828, 2022). "Using a mouse model of DMBA/TPA-induced skin cancer, we show that the levels of both PINCH-1 and IGF-1R were significantly increased in response to treatment with the carcinogens." (PMID 35401828, 2022). "Genetic ablation of PINCH-1 from the epidermis markedly reduced the IGF-1R expression and cell proliferation despite stimulation with DMBA/TPA, resulting in resistance to chemical carcinogen-induced skin cancer initiation and progression." (PMID 35401828, 2022).
viral infection (5 papers, 2015 to 2025). "To further link metabolic responses and inflammation, we assessed insulin signaling related genes, observing that viral infection significantly decreased transcriptional levels of igf1 and its receptor igf1r in the liver of IPNv challenged fish." (PMID 34768822, 2021). "Combining MYL3 and IGF1R inhibitors might offer a synergistic approach to prevent viral infection." (PMID 40560751, 2025). "A three-gene transcript signature, comprising HERC6, IGF1R, and NAGK, was derived from the discovery cohort of 56 participants with bacterial infections and 27 with viral infections." (PMID 34423323, 2021).
acute respiratory distress syndrome (4 papers, 2005 to 2023). Progressive and life-threatening pulmonary distress in the absence of an underlying pulmonary condition, usually following major trauma or surgery. "Likewise, the expression pattern of IGF-I and IGF-1R in the lung is altered in various diseases that require oxygen therapy, including cystic fibrosis, lung fibrosis, acute respiratory distress syndrome or bronchopulmonary dysplasia." (PMID 15819984, 2005). "We consider that the findings of our study will precipitate additional research efforts to assess whether interference with IGF-1R signaling may be a way of reducing or preventing the development of acute respiratory distress syndrome." (PMID 15819984, 2005). "Several studies demonstrate a mechanistic role for IGF1 in acute and chronic lung diseases, including acute respiratory distress syndrome (ARDS) with an upregulation of IGF1 and IGF1-R expression, but also inflammatory as well as fibrotic conditions." (PMID 34831169, 2021). "Interestingly, immunostaining for IGF1 and its receptor in lung tissue from individuals with acute respiratory distress syndrome showed increased expression of IGF1 and IGF1R." (PMID 25790853, 2015).
adrenal tumors (4 papers, 2012 to 2025). "The IGF1R copy number in 64 adrenal tumor samples was analyzed using MLPA in this study." (PMID 25110710, 2014).
Arthritis (4 papers, 2021 to 2025). Inflammation of a joint. "Next, a deep histological analysis of intracellular IGF1R signalling in spleen of arthritis mice was performed by staining IRS1 and FOXO1." (PMID 36105797, 2022). "In experimental arthritis, sufficient IGF1R signalling at the time of antigen challenge enabled the migration of inflammatory cells into the joints." (PMID 36105797, 2022). "It was also shown that IGF-1R signaling contributes to T cell dependent inflammation in arthritis." (PMID 41383600, 2025). "Inhibition of IGF1R signalling abolished T cell migration and alleviated arthritis." (PMID 36105797, 2022). "Similar to insulin, IGF-1R signaling plays a role in inflammation mediated by T cells in arthritis." (PMID 33995414, 2021).
childhood cancers (4 papers, 2011 to 2024). "In preclinical models of childhood cancers, the prototypical anti-IGF-1R antibody, α-IR3, mediated downregulation of IGF-IR, significantly retarded the growth of several cell lines in vitro, and inhibited the growth of pediatric cancer xenografts." (PMID 21197468, 2011).
gynecological cancer (4 papers, 2014 to 2025). "For the long term, we believe that restoring the TME function by IGF1R targeting in combination with immunotherapy can serve as a new clinical approach for gynecological cancers." (PMID 29922232, 2018).
Hodgkins lymphoma (4 papers, 2014 to 2017). A heterogeneous group of malignant lymphoid neoplasms of B-cell origin characterized histologically by the presence of Hodgkin and Reed-Sternberg (HRS) cells in the vast majority of cases. "There was a significant difference in IGF-1R expression with HL subtype (p = .0157), with a high percentage of positive cases in the nodular sclerosis cases (38/61) and a low percentage of positive cases in mixed cellularity cases (1/9)." (PMID 24489919, 2014).
hypothyroidism (4 papers, 2010 to 2026). Abnormally low levels of thyroid hormone. "BALB/c mice immunized with the TSHR A-subunit plasmid developed TSHR/insulin-like growth factor 1 receptor (IGF-1R) antibodies, hypothyroidism, orbital inflammation, and proptosis, mimicking TAO." (PMID 40605078, 2025).
injury (4 papers, 2014 to 2026). Damage inflicted on the body as the direct or indirect result of an external force, with or without disruption of structural continuity. "IGF1R defect reduces the inflammation area of lung tissue and proinflammatory markers but increases resolution indicators in the bleomycin-induced lung injury mouse model." (PMID 39479394, 2024). "On this basis, we aimed to study the implications of IGF1R on the inflammatory process that occurs during BLM-induced acute lung injury." (PMID 28655914, 2017). "Notably, although inhibition of IGF-1/IGF-1R signalling has different effects in a phase-dependent manner during the course of acute lung injury, IGF-1 stimulation consistently improves the conditions from the acute phase to the recovery phase." (PMID 41431237, 2026). "Our data show clearly that the expansion of SVZ NPs following brain injury requires EGFR and IGF-1R co-signaling." (PMID 24904523, 2014).
mammary adenocarcinomas (4 papers, 2008 to 2025). "In this study, we confirmed the expression levels of HIF-1α, IGF-1R and TOP2A proteins in mammary adenocarcinomas tissue." (PMID 40969744, 2025).
metastatic colorectal cancer (4 papers, 2016 to 2025). "Moreover, the invasion of cancer cells and resistance to multi-kinase inhibitors regorafenib and sorafenib were also associated with increased IGF-1R signaling in metastatic colorectal cancer and hepatocellular carcinoma." (PMID 36017326, 2022). "In their study, nuclear IGF-1R expression was detected by immunohistochemistry in 470 patients with metastatic colorectal cancer, with higher expression in tumors from patients that had undergone treatment." (PMID 40777019, 2025). "have demonstrated how nuclear IGF-1R can predict resistance to chemotherapy and targeted therapy in metastatic colorectal cancer." (PMID 40777019, 2025). "Another strategy is to combine the anti-EGFR mAb panitumumab with an anti-hepatocyte growth factor mAb rilotumumab or ganitumab, an anti-insulin-like growth factor 1 receptor (IGF-1R) mAb in metastatic colorectal cancer with wild-type KRAS (NCT00788957)." (PMID 29312320, 2017). "Recently, a phase II/III trial of dalotuzumab and anti IGF1R monoclonal antibody, with standard treatment as a salvage therapy in metastatic colorectal cancer was reported." (PMID 27144430, 2016).
neuroendocrine tumors (4 papers, 2014 to 2019). "Archival material should be available for revision according to WHO 2010 neuroendocrine tumor classification and for p-mTOR, SSTR2A, and IGF-1R immunostaining, calculating a quantitative score (QS)." (PMID 29213282, 2017).
Proptosis (4 papers, 2023 to 2025). An eye that is protruding anterior to the plane of the face to a greater extent than is typical. "The TSHR, along with the insulin-like growth factor-1 receptor (IGF-1R), activates orbital inflammation, resulting in proptosis (exophthalmos), diplopia, and periorbital swelling." (PMID 40718626, 2025).
retinoblastoma (4 papers, 2012 to 2025). A malignant tumor that originates in the nuclear layer of the retina. "In later life, miR-675 has various targets like the receptor insulin-like growth factor 1 receptor (IGF1R), which is involved in proliferation and migration or the tumor suppressor retinoblastoma (RB)." (PMID 32429417, 2020). "Noteworthy findings suggest that the upregulation of miR-153 leads to the suppression of its target gene IGF1R, thereby inhibiting the activation of the Raf/MEK and PI3K/AKT signaling pathways, consequently impeding the proliferation and invasion of retinoblastoma cells." (PMID 40535798, 2025).